BRCA1 (BRCA1 DNA repair associated)
Diseases named in the same sentence as BRCA1 in open-access papers (continued):
Sharing a sentence is not in itself a finding about the gene and the disease.
cancer (continued). "Our work points to the synergism between KLF4 and PARP1 in tumorigenesis and cancer therapy, which provides a potential new therapeutic strategy for killing BRCA1‐proficient triple‐negative breast cancer cells." (PMID 33231937, 2020). "Loss of one copy of functional BRCA1/2 is not clinically apparent, and somatic mutations detection of BRCA genes is affected by cancer cell content and mutation ratio, lacking the accuracy and inherent simplicity, and the accuracy of detection." (PMID 31998560, 2020). "Both the median age at cancer diagnosis and the family histories in our cohort are compatible with a reduced penetrance of BRCA1 c.5407-25T>A, although we were not able to calculate precise penetrance estimates due to the small number of patients." (PMID 32203205, 2020). "Approximately one in five breast cancer 1 (BRCA1) gene-expressing cancers also express Ars, but are negative for ERs and PRs." (PMID 32326308, 2020). "Generally, cancer cells lacking either of the tumor suppressors BRCA1 and BRCA2, which are key components in the HR pathway of DSB repair, are selectively sensitive to PARP family inhibitors." (PMID 32355263, 2020). "Previously reported findings suggesting that some cancers have only BRCA1 deleted but not BECN1 deleted, fail to hold true with increased growth and precision of the database of tumor CNAs." (PMID 31923184, 2020). "The data also indicated that tumors had a high heterogeneity, with mixed stromal cells seen within a single tumor, reflecting heterotypic interactions between cancer cells and noncancer cells in the Brca1 tumor microenvironment." (PMID 32978388, 2020). "These significant associations between miR-34 members and BRCA transcripts were identified only in BRCA1/2 wild-type cancers (data not shown)." (PMID 32047551, 2020). "It is important that LOH in the BRCA1/2 genes occurs within the tumor itself, but not the surrounding tissue and is an enabling characteristic of cancer development." (PMID 33015624, 2020). "We found no significant variation in HADS-A and HADS-D scores from baseline to follow-up in men without cancer receiving either positive or negative BRCA1/2 test results." (PMID 32089686, 2020). "This study found a 0.2% allele frequency for BRCA1, BRCA2, and PALB2 founder variants in controls with no personal or family history of cancer." (PMID 32300229, 2020). "As regards the association with overall cancer risk, the OR of LOF variant carriers versus nonsynonymous variant carriers was 1.53 (95% CI: 0.80–2.92) and 1.14 (95% CI: 0.40–3.22) for BRCA1 and BRCA2, respectively." (PMID 33266155, 2020). "In order to identify other BC/OC susceptibility genes/variants, especially in familial non-BRCA patients, panels for analysis of cancer-related genes other than BRCA1/2 were used as well." (PMID 31936873, 2020). "Twenty-two BRCA1 and BRCA2 germline variants were identified in 12 different cancer types, of which 10 (45%) were not previously identified in these patients based on the current clinical guidelines." (PMID 31263571, 2019). "Therefore, analysis of only BRCA1 and BRCA2 would explain the genetic etiology of cancer in just 10.5% (126/1197) of the individuals in our cohort." (PMID 31159747, 2019). "PTEN, BRCA1, BRCA2, PI3K, and CCND1 genes were related to the BREAST cancer signaling pathway." (PMID 30792708, 2019). "How can BRCA1 and BRCA2 gene testing in patients with cancer be increased?" (PMID 31125106, 2019). "Exploiting DNA repair defects present in cancer cells but absent in normal cells improves therapeutic responses, as demonstrated by the use of PARP-inhibitors (PARPi) in cancers that have BRCA1/2 deficiencies." (PMID 31596905, 2019). "In BRCA1/2-negatice breast cancer patients, although RAD50 pathologic germline mutations poses no increased risk of cancer, it is nevertheless associated with unfavorable survival." (PMID 31767017, 2019).
cancer (continued). "Wild type fibroblasts (i.e. BRCA1 proficient) did not undergo any malignant transformation after exposure to cancer EVs." (PMID 31200749, 2019). "This indicates that both the interaction with BRCA1 and BRCA2 is crucial for PALB2’s function in controlling G2/M-phase progression following DNA damage, which is in accordance with observations in human cancer cells." (PMID 31757951, 2019). "Although family and personal history are also utilized as part of decisions of when to recommend elevated cancer surveillance, BRCA1 and BRCA2 VUS identified in genetic screens do not inform such decisions." (PMID 30832243, 2019). "Besides, the BRCA1 and JAK2 that co-cited with ‘cancer’ and ‘breast’ for many times were also missed by the DawnRank." (PMID 31888619, 2019). "Targeting RAD52 in BRCA-depleted cancer cells will sensitize them to the toxic effect of DSBs, while normal cells and tissues with intact BRCA1/2-dependent HR should not be influenced." (PMID 31615159, 2019). "In the breast, as well as all other tissues, the BRCA1 and BRCA2 are expressed and involved in repair process of damaged DNA and any reduction or disruption of these two proteins could lead to cancer." (PMID 30642295, 2019). "We identified 6986 transcripts differently expressed between cancer EVs-exposed and non-exposed BRCA1-KO fibroblasts." (PMID 31200749, 2019). "CRRM might be recommended for BRCA1 cancers, while BRCA2 cancers may avoid CRRM through the use of thorough MRI surveillance and improvements in the indication and the technical skills required in MRI-guided biopsy." (PMID 30820924, 2019). "Here, we have undertaken this approach for BRCA1 and BRCA2 in 28 cancer types." (PMID 31360904, 2019). "Cells lacking functional BRCA1 or BRCA2 are deficient for double-stranded break repair, resulting in genomic instability that leads to cancer predisposition." (PMID 31379942, 2019). "These DSBs that normally would be repaired by HR with the sister chromatid duplex would be fixed inefficiently in certain cancers due to the absence of any one of the three key HR repair proteins BRCA1, BRCA2, or PALB2." (PMID 29998112, 2018). "However, TSGs are also important for cancer targeted therapy, since the discovery of synthetic lethality of the PARP1 and BRCA1/2 genes and their clinical applications using PARP inhibitors." (PMID 29805750, 2018). "To date, 61 missense mutations (70.5% in BRCA1 & 29.5% in BRCA2) have been documented; however, it is not yet clear if patients have higher cancer risk depending on the type of BRCA mutation." (PMID 30766717, 2018). "Mutations of BRCA1 and BRCA2 genes considerably increase an individual’s risk of OC;7 combined with non-genetic information (eg, family history of cancer, age and lifestyle factors), this genetic information can be used to estimate a woman’s risk." (PMID 30021754, 2018). "We should emphasize that until 2016, genetic studies regarding HBOC were practically limited to the BRCA1/BRCA2 genes, mainly due to the high cost of Sanger and MLPA sequencing techniques, but at present, most Familiar Cancer Units use gene panels related to HBOC." (PMID 29884136, 2018). "Cancer cells lacking functional BRCA1 or BRCA2, critical players in HRR, were found to be particularly sensitive to PARP1 inhibition." (PMID 29684820, 2018). "Hypoxia induced by antiangiogenic agents seem to downregulate BRCA1/2 and RAD51 in cancer cells." (PMID 30347758, 2018).
cancer (continued). "Inherited variation in the BRCA1 and BRCA2 genes can indicate genetic predisposition to breast, ovarian, and other cancers, but a large proportion of observed variants are not disease associated ("pathogenic")." (PMID 30586411, 2018). "Men with a previous diagnosis of BC were included, from the beginning of our program, since we considered male BC as criteria for BRCA1/2 testing, even without other cancer family history." (PMID 29456621, 2018). "BRCA1-associated cancers are more likely to present specific characteristics like the absence of ER, PR, and HER2 receptors, unlike BRCA2-related cancers, which usually express ER and PR." (PMID 30249004, 2018). "All but one individual with a positive NBN screening result had a negative family history for cancer, with the negative result of the BRCA1/2 screening." (PMID 30441849, 2018). "We found FAM35A absent in one widely used BRCA1‐mutant cancer cell line with anomalous resistance to PARP inhibitors." (PMID 29789392, 2018). "Here, we have seen that in presence of CAFs, there is a strong loss of epithelial markers and a modest increase in mesenchymal markers in BRCA1 mutant but not wild type cancer cells confirming the onset of EMT." (PMID 30224826, 2018). "Although they were not sequenced for BRCA1 and BRCA2 mutations, their advanced age and the lack of a family history of cancer make them unlikely to be mutation carriers." (PMID 29433565, 2018). "Furthermore, we found a positive correlation between BRCA1 and the three target genes in cancer cell lines and verified FADD as a novel direct target of BRCA1 by luciferase reporter, ChIP, and functional studies." (PMID 29757984, 2018). "Considering the frequency of pathogenic variants of high-penetrance genes in patients with early-onset cancer, clinicians should be encouraged to consider performing multigene panel tests for these patients if their conventional BRCA1/2 tests are negative." (PMID 29338689, 2018). "The onset age of BRCA1/2 carriers was younger than that of non-carriers, supporting the fact that BRCA genes are a potential cancer risk factor." (PMID 29152070, 2017). "These include cancer hallmarks of various types: oncogenes (BCL2, BRAF), caspases (CASP6/7), transcription factors (E2F3), cell cycle genes (CDC42, CDK2, CDKN2A), cancer related kinases (JAK2/3, MAPK4/6/14) and DNA repair genes (BRCA1, PARP1 and RAD50)." (PMID 28059167, 2017). "Some of them were cancer-related according to COSMIC and HGMD databases (no founder mutations in BRCA1 and BRCA2 have been found)." (PMID 28787462, 2017). "Interestingly, recent findings indicate that the presence of BRCA1 mutations is associated with augmented proliferation of luminal progenitor cells and, thus, JQ1 could be used in pre-neoplastic tissue to block these hyperactive cells in their course towards full cancer development." (PMID 28881673, 2017). "Supporting the idea that some of the associations in WGA cancer types are false, only two of the significant genes (BRCA1/2) in OV and none in LAML are genes where germline variation is known to be associated with cancer risk." (PMID 28606096, 2017). "Using ChIP and luciferase assays, we also demonstrated that the cancer cells with wild-type but not mutant BRCA1 directly repress the expression of β-hCG by binding to its promoter." (PMID 28869585, 2017). "We found that BRCA1 and ERCC1 proteins were located in the nuclei of cancer cells." (PMID 28404895, 2017).
cancer (continued). "Tissue microarray statistical results showed that the expressions of BRCA1 and MAPTin cancer tissues were significantly lower (p<0.01) than that in adjacent tissues, whereas the expressions of STMN1 and TUBB3 in cancer tissues were significantly higher (p<0.01) than that in adjacent tissues." (PMID 29113350, 2017). "Survival analysis was conducted among 68 patients with stage 0–III cancer, including 14 BRCA1/2 carriers and 54 non-carriers." (PMID 29152070, 2017). "Without HR and the RAD52-dependent backup pathway, the BRCA1 mutant cancer cells depleted of EEPD1 skew to the alternative non-homologous end-joining DNA repair pathway for survival." (PMID 29145865, 2017). "Most cancers in non-carriers or in CHEK2 carriers are ER-positive whereas cancers in BRCA1 carriers are usually triple-negative and these are relatively aggressive in their natural history." (PMID 28265306, 2017). "Our initial results showed that micromolar concentrations of vorinostat could lead to a major reduction in the level of BRCA1 and RAD51 and as expected vorinostat led to increased sensitivity of various cancer cell lines to ABT-888." (PMID 27196668, 2016). "This work highlights the fact that BRCA1-mutant and TNBCs are a heterogeneous groups of cancers that are not benefitting from the current “one size fits all” standard of care chemotherapy." (PMID 26943587, 2016). "To investigate whether the effect of BRCA1 knockdown on cell viability is unique to GBM cancer cells, we have tested additional four cancer cell lines." (PMID 27845331, 2016). "In future research, it will be interesting to determine whether the CES genes act synergistically with other genes involved in genome maintenance, such as BRCA1 and BRCA2 (refs 71, 72), to promote cancer progression." (PMID 27577169, 2016). "Since the original description of a SL interaction between PARP and BRCA1/2 in 2005, PARP inhibitors have garnered substantial attention as novel compounds for precision medicine based approaches in the fight against cancer." (PMID 27902462, 2016). "Breast and high-grade serous OC share common genetic and non-genetic risk factors, with mutations in BRCA1 and BRCA2 the most significant risk factors for both cancers, suggesting similar biological mechanisms drive breast and OC development." (PMID 27601076, 2016). "Generation of a “BRCA1 basal” miRNA and immunohistochemical profile in FFPE tissue may identify patients with basal type cancers who will require BRCA1 genetic testing." (PMID 26152113, 2015). "Four percent of cancer samples and none of the adjacent or control mammoplasty samples displayed BRCA1 methylation in excess of 20 % (results not shown)." (PMID 26510686, 2015). "There was a trend for lower mir-190b expression in BRCA1 cancers, although this was not statistically significant (p = 0.0914)." (PMID 26152113, 2015). "Autoantibody frequency to PARP1, BRCA1, and BRCA2 in cancer varied from 0% to 50%." (PMID 25865228, 2015). "Similarly, BRCA1 and CHEK2 were suggested to participate in cancer development by modulating DNA repair and cell cycle checkpoints in collaboration with FOXM1 and E2F1, respectively." (PMID 26001967, 2015). "Notably, a recent report suggested the action of positive selection on the evolution of BRCA1 and RHAMM orthologs in the naked mole rat, which is an exceptionally cancer-resistant species." (PMID 25830658, 2015). "Here, in this study, we analyzed the aberrant promoter methylation profile of HNSCC using seven important tumor-related pathway genes (p16, DAPK, GSTP1, ECAD, RASSF1, MLH1 and BRCA1) and three methylated loci (MINT1, MINT2 and MINT31) in the high cancer incidence zone of Northeast India." (PMID 26098903, 2015).
cancer (continued). "The genomic instability of BRCA1- and BRCA2-defective cells can be exploited for cancer therapy." (PMID 25769025, 2015). "We identified damaging mutations in ATR, BRCA1/2, MAP4K1, CUL3 and MAX, already reported in other cancer types but not described yet as mutated in PTC." (PMID 25803323, 2015). "Increased expression for CD99 in BRCA1 cancers was not reproduced in the validation cohort, where reduced expression was observed." (PMID 26152113, 2015). "We compared the WGS results from the BRCA1/2-carrier cohort (n = 176) to the non-BRCA cancer genetics clinic cohort (n = 82) using a “gene variance” analysis." (PMID 26023681, 2015). "Besides, we observed varying expression of APLF, BRCA1, WRN and LIGASE I in normal and cancer cells." (PMID 25789972, 2015). "With respect to hormone receptor expression, BRCA1 mutant carcinomas were significantly more frequently found to be ER negative (p = 0.001), PR negative (p = 0.001) or even triple negative (p = 0.002)." (PMID 26029931, 2015). "miR-638 has been reported to inhibit BRCA1 expression in different cancer cell lines by targeting BRCA1 in CDS, but not in 3’ UTR." (PMID 25228385, 2014). "Although the significance of these MNAN-induced tumors is not yet understood in human BRCA1-related cancers, these results suggest that Brca1 is involved in the regulation of ROS in carcinogenesis of the mouse." (PMID 24704793, 2014). "Even though we have focused on BRCA1/2 inactivation in impaired HR function, the frequency of BRCA1/2 mutations does not explain all cases of HR impairment in BRCA-associated cancers." (PMID 25158060, 2014). "Depletion and inhibition of the activity of CDK1, which phosphorylates BRCA1 and is necessary for the formation of BRCA1 foci and DNA damage repair by HR, was also reported to sensitize cancer but not the untransformed cells to PARP inhibition." (PMID 25026298, 2014). "Tumor suppressors PRF1 and BRCA1, as well as oncogene TFEB, all of which may play an important role in cancer cell survival during the progress of metastasis, were predicted as driver genes only in metastases." (PMID 24405831, 2014). "Epigenetic lesions in DNA without mutations in the coding regions have been shown to be common phenomena in the pathogenesis of a wide range of cancers, especially the methylation-mediated silencing of tumor suppressor genes such as VHL, p16INK4a, E-cadherin, hMLH1, BRCA1, and LKB1." (PMID 24829571, 2014). "Non-silent mutations of BRCA1, PRF1, and other cancer genes were detected solely in the metastasis stage." (PMID 24405831, 2014). "Almost all of the BRCA1 and BRCA2 variants observed in our cohort are unlikely to have strong effects on cancer susceptibility." (PMID 24728327, 2014). "The effect of lestaurtinib are primarily on G2 arrest, apoptosis and reduced proliferation of cancer cells irrespective of their BRCA1 status." (PMID 24962108, 2014). "BRCA1 methylation was detected in 50 (35.2%) of the 142 carcinomas, however, no methylation was detected in the benign tumors." (PMID 24944674, 2014). "Although cancer does not develop in plants, a homolog of BRCA1 (AtBRCA1) is found in A. thaliana genomes." (PMID 24833228, 2013). "For the cancer phenotypes, the reverse genetics models were enriched in DNA repair functions (p = 2×10−5, FDR p = 0.03) (POLG/FANCI, SLX4/FANCP, XRCC1, BRCA1, FANCA, CHD1L) while the additive model showed enrichment related to chromatid segregation (p = 4×10−6, FDR p = 0.005) (KIF25, PINX1)." (PMID 24349080, 2013). "High frequencies of ALDH+ cells were found in the non-basal ductular levels in BRCA1 mutation carriers (p = 0.03), but in the basal ductular level in BRCA2 cancer patients (p = 0.02)." (PMID 24188377, 2013). "For example, BRCA2 functions in RAD51 loading and BRCA1 in countering 53BP1-mediated blocking of homologous recombinational (HR)-DNA repair; hence poly (ADP-ribose) polymerase (PARP) inhibitors have been developed and trialled against BRCA-driven cancers." (PMID 24286369, 2013).